RET (ret proto-oncogene)
Diseases named in the same sentence as RET in open-access papers (continued):
Sharing a sentence is not in itself a finding about the gene and the disease.
thyroid cancer (continued). "The prevalence of RET fusions is greater in radiation-induced thyroid cancer (approximately 60–80%)." (PMID 41278287, 2025). "Chromosomal rearrangements involving genes known to be translocated in thyroid cancer were found in two samples, including one case with RET rearrangement involving the common RET partner CCDC6 and one case with the PAX8::PPARG fusion." (PMID 41123735, 2025). "The most frequent RET fusions have been observed in thyroid cancer (approximately 3% of all cases and 9–11% of the papillary subtype) and in lung adenocarcinoma (approximately 1%)." (PMID 41373459, 2025). "Subgroup analyses in patients with other RET fusion-positive tumors other than lung or thyroid cancers are necessary to provide real-world evidence of selpercatinib in other populations observed in clinical trials." (PMID 39594790, 2024). "In the case of selpercatinib, FDA accelerated approval was based on a cohort of 19 patients with RET-fusion-positive thyroid cancer (including three with poorly differentiated and two with anaplastic tumors), 15 of whom responding to treatment." (PMID 38427812, 2024). "Other genetic mutations reported in various thyroid cancer include RAS PIK3CA, AKT1, PTEN, mTOR, and chromosomal rearrangements involving RET/PTC and PAX8-PPARɣ genes." (PMID 39724083, 2024). "Recent advancements spotlight the efficacy of selpercatinib, a selective RET inhibitor, particularly in non-small cell lung cancer and RET-positive thyroid cancer, even extending to a tissue agnostic approval." (PMID 39272672, 2024). "Selpercatinib, a highly selective and potent oral REarranged during Transfection (RET) inhibitor, is approved for treating RET-altered lung cancer, thyroid cancer, and other solid tumors in the United States." (PMID 39594790, 2024). "Beyond lung and thyroid cancer, a recent case reported a patient with RET fusion-positive pleiomorphic sarcoma that responded to a neoadjuvant RET inhibitor and that the neoadjuvant reduction in tumor glucose activity and size was assessed by FDG PET." (PMID 39272672, 2024). "Comparing molecular testing for key mutations of thyroid cancer, such as BRAF V600E and RET, is important among Hispanics and other races/ethnicities and within Hispanic subgroups." (PMID 38539437, 2024). "Selpercatinib, a first-in-class, highly selective, and potent RET kinase inhibitor with CNS activity, was approved in the United States for the treatment of RET-activated, advanced, or metastatic lung and thyroid cancers." (PMID 39594790, 2024). "A number of case reports or case series for neoadjuvant purposes have been published in different pathological types of thyroid cancer, such as BRAF V600E–mutated anaplastic thyroid carcinoma and medullary thyroid cancer with RET mutation." (PMID 39071474, 2024). "RET rearrangements are present in about 10%–20% of thyroid cancers and 1%–3% of non-small cell lung cancer (NSCLC) cases, making routine testing for RET fusions at diagnosis advisable." (PMID 39372206, 2024).
thyroid cancer (continued). "Selpercatinib has also exhibited promising activity in other RET-driven malignancies, including RET fusion-positive thyroid cancer and other solid tumors with RET gene fusions." (PMID 39272672, 2024). "The recommended pralsetinib dose for the treatment of patients with metastatic RET fusion-positive NSCLC or thyroid cancer is 400 mg orally once daily; however, a lower dose of 200 mg pralsetinib was administered to subjects enrolled in this study." (PMID 38675225, 2024). "Abnormal activation of the RET kinase can lead to several cancers, including thyroid cancer and non-small-cell lung cancer." (PMID 38397034, 2024). "In conclusion, this report underscores the efficacy of selpercatinib for RET fusion-positive tumors beyond lung and thyroid cancers, supporting its integration into the treatment paradigm for diverse RET-altered malignancies." (PMID 39085487, 2024). "Pralsetinib, a selective oral inhibitor of rearranged during transfection (RET) fusion proteins and oncogenic RET mutants, has shown significant efficacy in treating RET fusion-positive non-small cell lung cancer and thyroid cancer." (PMID 39600647, 2024). "In a phase I-II trial(NCT03157128), selpercatinib showed durable efficacy in 19 patients with previously-treated RET fusion-positive thyroid cancer, and the response rate was 79% (95% CI, 54–94)." (PMID 39473507, 2024). "The oncogenic translocation RET/PTC1 is present in more than 70% of radiation-induced thyroid cancers." (PMID 39047147, 2024). "The clinically most relevant, frequently occurring and selectively targetable, gene alterations in thyroid cancer are the different types of BRAF, RET, NTRK, and MET mutations." (PMID 39409115, 2024). "In the ARROW study (NCT03037385), the ORR of pralsetinib in 22 previously treated RET fusion positive thyroid cancer patients was 90.9% (95%CI: 70.8-98.9)." (PMID 39473507, 2024). "RET/PTC1 (coiled‐coil domain containing 6 [CCDC6]‐rearranged during transfection) rearrangement is a distinctive feature in over 70% of thyroid cancers who exposed to low doses of IR in Chernobyl and Hiroshima‒Nagasaki atomic bombings." (PMID 39135916, 2024). "DSPTC carries various genetic alterations, with most frequent the RET fusion in 32%, followed by BRAFV600E mutations in around 20%, and the novel gene for thyroid cancer, USP8 in 10%." (PMID 39458070, 2024). "Papillary thyroid cancer, which accounts for a large percentage of thyroid cancers, is distinguished by changes in expression of specific oncogenes that drive tumor growth, which includes RET proto-oncogene." (PMID 39766189, 2024). "Genetic alternation of REarranged during Transfection (RET) that leads to constitutive RET activation is a crucial etiological factor for thyroid cancer." (PMID 38378752, 2024). "Two RET inhibitors, selpercatinib and pralsetinib, are the standard treatment option for RET-driven thyroid carcinomas as well as for RET-rearranged non-small cell lung cancers." (PMID 38612902, 2024). "In thyroid carcinoma, the frequency of RET fusion genes ranges from approximately 6 to 10%, which aligns with our results." (PMID 38472412, 2024). "Thyroid carcinomas exhibit various genetic alterations, including the RET and NTRK fusion genes that are targets for molecular therapies." (PMID 38472412, 2024). "Based on this advancement, we conducted detailed pathological examinations of thyroid carcinomas in which the RET and NTRK3 fusion genes were identified using the Oncomine Dx Target Test." (PMID 38472412, 2024). "The Food and Drug Administration has approved therapeutic options for the treatment of advanced BRAFV600E-mutated thyroid carcinomas, NTRK fusions, RET-mutated medullary thyroid carcinoma, and RET-fusion papillary thyroid cancer." (PMID 38541982, 2024). "An oncogenic RET rearrangement, a known driver of cribriform morular thyroid carcinoma, was also found in this tumor." (PMID 38415346, 2024).
thyroid cancer (continued). "This phase 1/2 study included 19 patients with RET fusion-positive thyroid cancers, mainly PTCs (13/19)." (PMID 37435488, 2023). "The results of this trial will inform the sequence of initiation of this novel selective RET inhibitor, and pending are trials of selpercatinib and pralsetinib early in the course of thyroid cancer." (PMID 37207147, 2023). "The selective RET inhibitors selpercatinib and pralsetinib are an advance in the treatment of RET-driven thyroid cancer." (PMID 37207147, 2023). "The thyroid cancer cohort of ARROW included patients with RET-mutant MTC, either previously untreated or with progression on cabozantinib and/or vandetanib, as well as patients with previously treated RET-rearranged thyroid cancer." (PMID 37627175, 2023). "The introduction of new targeted therapies for RET-altered lung and thyroid cancers (LC/TC) has impacted pathologists’ practice by making genomic testing more relevant." (PMID 37277734, 2023). "A recently published case series did not demonstrate impaired wound healing or other surgery-associated complications with neoadjuvant selpercatinib followed by surgery for locoregionally advanced RET-altered thyroid cancer patients." (PMID 38118420, 2023). "Phase Ib dose expansion will evaluate LOXO-260 in specific expansion cohorts: RET fusion–positive NSCLC or thyroid cancers and RET-mutant MTC." (PMID 38201460, 2023). "Many invasive tumors (e.g., non-small cell lung cancer, thyroid cancer, and breast cancer) were found to have changes in RET." (PMID 36865807, 2023). "The growth inhibitory effects of the Src inhibitor, dasatinib, in combination with the MEK1/2 inhibitor trametinib were analyzed in 23 thyroid cancer cell lines expressing clinically relevant mutations (BRAF, RAS, RET/PTC1)." (PMID 36672327, 2023). "Multiple pre-clinical models of NSCLC and MTC have been used to highlight the possibility of potent RET inhibition by Pralsetinib, which was FDA-approved for the treatment of RET-altered thyroid cancers in December 2020." (PMID 36918928, 2023). "Owing to the promising results, selpercatinib received accelerated approval for the treatment of patients with RET-mutant MTC or advanced or metastatic RET fusion-positive thyroid cancer in 2020." (PMID 36646686, 2023). "Three cohorts (RET fusion–positive NSCLC or thyroid cancers and RET-mutant MTC) at RP2D were expanded in eligible patients." (PMID 38201460, 2023). "Integration of genomic biomarker testing for RET-altered lung and thyroid cancers varies by country and clinical setting." (PMID 37277734, 2023). "Rearranged during transfection (RET) fusions are common genetic drivers of PTC and the potent RET inhibitor selpercatinib has been recently approved for treating advanced or metastatic RET fusion-positive thyroid cancer." (PMID 37081420, 2023). "The indications for which it has been approved for adolescents are medullary thyroid cancer and RET-fusion-positive thyroid cancer." (PMID 38118420, 2023). "Summary of phase I/II trial results of the selective RET inhibitors approved in Europe for the treatment of RET-driven advanced thyroid cancer according to Response Evaluation Criteria in Solid Tumors (RECIST)." (PMID 37207147, 2023). "In this context, selpercatinib (NCT04759911) and the MKI lenvatinib (NCT04321954), initiated prior to surgery, are being investigated in clinical studies in patients with RET-altered thyroid cancer and will provide answers soon." (PMID 37207147, 2023). "Selpercatinib, a novel and highly selective inhibitor of RET kinase, with demonstrated CNS activity, has been proven effective in the treatment of RET fusion-positive lung and thyroid cancers." (PMID 38001751, 2023). "RET gene fusions are present in between 1% and 2% of NSCLC and thyroid cancers and represent potential targets for therapeutic inhibition of RET kinase." (PMID 36900367, 2023).
thyroid cancer (continued). "There were 144 NSCLC patients, 143 MTC patients, and 19 RET fusion–positive thyroid cancer patients evaluable for efficacy." (PMID 38201460, 2023). "Based on the findings of this trial, the FDA approved pralsetinib for adult and pediatric patients with advanced or metastatic RET-fusion-positive lung and thyroid cancers for whom systemic therapy is indicated." (PMID 36900367, 2023). "The p27 modulation is in agreement with the already described reduction of p27 levels upon expression of RAS, BRAF or RET/PTC mutants in thyroid cancer cells, which would be reversed by MEK inhibition." (PMID 37964967, 2023). "The Rearranged during Transfection (RET) protooncogene encodes a receptor of the tyrosine-kinase proteins and has been associated with numerous types of cancers, including thyroid cancer." (PMID 37189693, 2023). "Efficacy of selpercatinib in RET-altered thyroid cancers was demonstrated in the LIBRETTO-001 trial." (PMID 37435488, 2023). "Following the LIBRETTO-001 trial, Selpercatinib was approved by the US FDA for the treatment of RET-fusion positive NSCLC, RET-mutant driven MTC, and other RET-fusion driven thyroid cancers refractory to radioactive iodine therapy." (PMID 36918928, 2023). "High expression of VEGFA and VEGFC showed favorable responses to various drugs, including BLU-667, which abrogates RET signaling, an oncogenic driver in liver and thyroid cancers." (PMID 37852616, 2023). "In a trial of the novel selective RET inhibitor selpercatinib that reported data from 19 patients with RET fusion-positive, previously treated thyroid cancer, objective responses were seen in 79%." (PMID 37434642, 2023). "As such, ESMO and the European Thyroid Association (ETA) clinical practice guidelines for thyroid cancer recommend that all patients with clinically apparent sporadic MTC are offered genetic counselling and screening for germline RET mutations." (PMID 37207147, 2023). "RET alterations have been identified in diverse thyroid cancer subtypes, and its fusions have been demonstrated to be a common oncogenic driver event of papillary thyroid carcinoma." (PMID 37221474, 2023). "Patients with RET fusion-positive cancer, excluding non-small-cell lung cancer and thyroid cancer, were encompassed in the efficacy-evaluable tumor-agnostic population." (PMID 38001751, 2023). "In previously treated RET fusion-positive thyroid cancer patients, most of which of papillary or poorly differentiated histology, the ORR was 64%." (PMID 37627175, 2023). "The most frequently associated genes with thyroid cancer found on PubMed were BAX, XRCC1, XRCC3, XPO5, IL-10, BRAF, RET, and K-RAS." (PMID 37211566, 2023). "Results from LIBRETTO-001 led to the US FDA regulatory approval of selpercatinib for the treatment of patients with RET fusion-positive NSCLC, RET fusion-positive thyroid cancers, and RET-mutant MTC in 2022." (PMID 37627175, 2023). "A total of 90% of thyroid cancers have identifiable driver mutations, which often are components of the MAPK pathway, including BRAF, RAS, and RET-fusions." (PMID 36672327, 2023). "Excitingly, the first RET inhibitor selpercatinib (Retevmo) was recently approved to treat non-small-cell lung cancer and two forms of thyroid cancer that contain RET alterations." (PMID 36765275, 2023). "Pralsetinib (BLU-667) is a second, potent, ATP-competitive, selective RET TKI which has been approved by the FDA for the treatment of RET fusion-positive NSCLC and RET-altered thyroid cancers based on the results of the registrational ARROW trial." (PMID 37627175, 2023). "A recent clinical trial showed that 79% of patients with previously treated RET fusion- positive thyroid cancer had a response to RET kinase specific inhibitor selpercatinib." (PMID 37081420, 2023). "Updated data presented at the 2022 American Society of Clinical Oncology (ASCO) meeting in 21 patients with previously treated RET fusion-positive thyroid cancers showed an ORR of 86% (95% CI 64-97), including 15 PRs." (PMID 37435488, 2023).
thyroid cancer (continued). "Since the ddPCR system established in this study provides a sensitive method for RET fusion detection, it would be definitely benefits more thyroid cancer patients in the clinic." (PMID 37081420, 2023). "Recently, selpercatinib, a highly selective inhibitor of RET receptor tyrosine kinase, has been used for RET-altered thyroid cancer." (PMID 36975442, 2023). "Activating RET mutations and rearrangements have been identified as actionable drivers of oncogenesis in numerous cancer types, including NSCLC and thyroid cancers." (PMID 38201460, 2023). "In RET-mutant medullary thyroid cancer and RET-fusion-positive thyroid cancers with different fusion partners, similar response rates were observed." (PMID 36469155, 2023). "In 19 patients with previously treated RET fusion–positive thyroid cancer, 79% had a response (95% CI: 54–94) and 1-year PFS was 64% (95% CI: 37–82)." (PMID 38201460, 2023). "The following ORRs were observed: 71% in treatment-naïve MTC patients, 60% in MTC patients with prior cabozantinib and/or vandetanib, and 89% in previously treated RET fusion-positive thyroid cancer patients." (PMID 37627175, 2023). "Among 183 cases of thyroid cancer with both PTC and MTC, 112 cases underwent gene testing and 24 cases (21%) showed a RET gene mutation, five cases had embryogenic mutations, 19 cases had systemic mutations, and the other 8.33% had the V804M gene mutation." (PMID 37580706, 2023). "This study describes concrete educational needs for providers involved in the care of patients with RET-altered thyroid carcinomas." (PMID 37574538, 2023). "With its reduced costs, there are increasing applications for its use, particularly in the space of emerging small, targetable therapeutics for advanced thyroid cancers, particularly those with variants in BRAF, RET or kinase fusions." (PMID 37510219, 2023). "The oncogenes activated in thyroid carcinomas, RET/PTC, RAS, and BRAF, by triggering the MAPK cascade, can induce a proinflammatory transcriptional program in thyrocytes, which mainly includes cytokines, chemokines, and their receptors." (PMID 37959281, 2023). "Patients with a personal or family history of thyroid carcinoma or MEN were excluded from the study, as were those with known mutations of the RET proto-oncogene." (PMID 37190260, 2023). "RET-fusions have been identified in several cancer types including 2% of lung carcinomas, 10–20% of thyroid carcinomas and in low frequency in other tumors." (PMID 36469155, 2023). "Pralsetinib, another kinase inhibitor, can inhibit RET fusions and mutations and has been indicated for the treatment of RET-mutant MTC as well as RET fusion-positive thyroid carcinoma." (PMID 37345200, 2023). "BRAF V600E and RAS mutations have been identified as the primary genetic drivers in thyroid carcinomas, followed by fusions involving RET and other receptor tyrosine kinases." (PMID 37124750, 2023). "ARROW is a phase 1/2 trial evaluating the efficacy of pralsetinib in patients with RET-altered locally advanced or metastatic solid tumors, including thyroid carcinomas." (PMID 37435488, 2023). "Using the TCGA thyroid cancer cohort, we found that the zebrafish RET gene signature is enriched in human thyroid cancers that harbor RET rearrangements, consistent with a conservation of gene expression in the zebrafish model." (PMID 35510953, 2022). "Further characterization of PTC tumors determined that RET proto-oncogene expression is primarily found in PTC subtype of thyroid cancers." (PMID 35957881, 2022).